BRCA2 (BRCA2 DNA repair associated)
Description:
Tumor suppressor protein that maintains genome stability primarily by repairing damaged DNA through homologous recombination (HR). Facilitates the repair of double-strand breaks (DSBs) by binding and mediating the loading of the RAD51 protein onto single-stranded DNA (ssDNA), thereby promoting the activity of RAD51, which catalyzes DNA strand exchange. BRCA2 nucleates and stabilizes RAD51 on ssDNA directly and delivers RAD51 to ssDNA-double-stranded DNA (dsDNA) junctions by sliding along dsDNA backbone. RAD51 targeting to ssDNA promotes removal of replication protein-A (RPA) from ssDNA and stabilization of RAD51-ssDNA filaments by blocking ATP hydrolysis. May play a role in the extension step after strand invasion at replication-dependent DNA double-strand breaks; together with PALB2 is involved in both POLH localization at collapsed replication forks and DNA polymerization activity. Required to prevent R-loop-associated DNA damage and thus transcription-associated genomic instability. Silencing of BRCA2 promotes R-loop accumulation at actively transcribed genes in replicating and non-replicating cells, suggesting that BRCA2 mediates the control of R-loop associated genomic instability, independently of its known role in homologous recombination. Also promotes RAD51 loading to telomeric regions, facilitating telomere replication and capping. Also required for homologous recombination during meiosis by promoting the recruitment of RAD51 and DMC1 recombinases to meiotic DSB sites, enabling proper chromosome pairing and crossing over. Also promotes homologous recombination by inactivating the FIGNL1-FIRRM complex to protect RAD51 filament from premature disassembly. Together with NPM1, may also regulate centrosome duplication.
Synonyms: FACD; FANCD1; FAD; FAD1; BRCC2; XRCC11; BROVCA2; FANCD; GLM3; PNCA2
Tractability: Small molecule: a structure with a bound ligand is known. PROTAC: UniProt records ubiquitination sites on it; ubiquitination databases record sites on it.
Gene: Protein-coding gene on chromosome 13 (32,315,086 to 32,400,268, forward strand). Ensembl gene ENSG00000139618.
Subcellular location: Chromosome; Chromosome, telomere; Nucleus; Cytoplasm, cytoskeleton, microtubule organizing center, centrosome
Subcellular location (Human Protein Atlas): Nucleoplasm; Cytosol
Pathways (Reactome):
Disease: Defective HDR through Homologous Recombination Repair (HRR) due to PALB2 loss of BRCA1 binding function; Defective HDR through Homologous Recombination Repair (HRR) due to PALB2 loss of BRCA2/RAD51/RAD51C binding function; Defective homologous recombination repair (HRR) due to BRCA1 loss of function; Impaired BRCA2 binding to PALB2; Impaired BRCA2 binding to RAD51; Impaired BRCA2 binding to SEM1 (DSS1); Impaired BRCA2 translocation to the nucleus
DNA Repair: HDR through Homologous Recombination (HRR); HDR through MMEJ (alt-NHEJ); Homologous DNA Pairing and Strand Exchange; Presynaptic phase of homologous DNA pairing and strand exchange; Resolution of D-loop Structures through Holliday Junction Intermediates; Resolution of D-loop Structures through Synthesis-Dependent Strand Annealing (SDSA)
Reproduction: Meiotic recombination
Gene Ontology:
Molecular function: double-stranded DNA binding; gamma-tubulin binding; histone acetyltransferase activity; identical protein binding; molecular function inhibitor activity; protease binding; protein binding; protein-macromolecule adaptor activity; single-stranded DNA binding
Biological process: cellular response to ionizing radiation; centrosome duplication; DNA damage response; DNA recombinase assembly; double-strand break repair; double-strand break repair involved in meiotic recombination; double-strand break repair via homologous recombination; establishment of protein localization to telomere; mitotic recombination-dependent replication fork processing; negative regulation of mammary gland epithelial cell proliferation; nucleotide-excision repair; positive regulation of DNA-templated transcription; regulation of DNA damage checkpoint; DNA recombination; DNA repair; male meiosis I; telomere maintenance via recombination
Cellular component: BRCA2-MAGE-D1 complex; centrosome; chromosome, telomeric region; DNA repair complex; lateral element; nuclear ubiquitin ligase complex; nucleoplasm; nucleus; protein-containing complex; secretory granule; site of double-strand break; cytosol; chromosome; cytoplasm
Genetic constraint (gnomAD): Loss-of-function variants: 188 observed, 264.34 expected, observed/expected ratio (o/e) 0.71, 90% interval 0.63 to 0.8. The upper end of that interval is the gene's LOEUF score, 0.8, which puts it in group 3 of 6, group 1 being the genes least tolerant of losing a copy. Missense variants: 3,781 observed, 3,957 expected, observed/expected ratio (o/e) 0.96, 90% interval 0.93 to 0.98. Synonymous variants: 1,258 observed, 1,362.8 expected, observed/expected ratio (o/e) 0.92, 90% interval 0.88 to 0.97.
Gene-disease validity (ClinGen):
ClinGen rates the evidence that BRCA2 causes each of these diseases.
BRCA2-related cancer predisposition (autosomal dominant): Definitive. Hereditary cancer predisposition due to variation(s) in the BRCA2 gene.
Fanconi anemia complementation group D1 (autosomal recessive): Definitive.
Cancer hallmarks: genome instability and mutations (suppresses); escaping programmed cell death (suppresses)
Homologues: Orthologues: chimpanzee BRCA2 (99% identical), macaque BRCA2 (91% identical), rabbit BRCA2 (69% identical), pig BRCA2 (69% identical), guinea pig BRCA2 (59% identical), mouse Brca2 (57% identical), rat Brca2 (57% identical), tropical clawed frog brca2 (29% identical), zebrafish brca2 (20% identical).
Diseases named in the same sentence as BRCA2 in open-access papers:
BRCA2 is named in the same sentence as 527 diseases in open-access papers, as found by Europe PMC text mining. Sharing a sentence is not in itself a finding about the gene and the disease. The quoted sentences say what the papers report.
breast cancer (3,428 papers, 1995 to 2026). A primary or metastatic malignant neoplasm involving the breast. "Given her early-onset breast cancer, genetic testing of her hereditary cancer risk revealed BRCA2 and MLH1 germline variants, confirming MINAS syndrome." (PMID 42016816, 2026). "Because he had a family history of breast cancer, he underwent genetic testing and was found to have a BRCA2 gene mutation (c.331_347delinsC [p.Asn111Leufs∗5])." (PMID 41769367, 2026). "Patients with BRCA1 or BRCA2-mutated carriers are advised to consider prophylactic bilateral mastectomy (PBM) which has been shown to reduce the incidence of breast cancer by approximately 90%." (PMID 41488281, 2026). "The French LIBER Trial is studying the effect of letrozole, given at a dose of 2.5 mg daily for 5 years, in the primary prevention of breast cancer among 171 unaffected postmenopausal women aged 40 - 70 years with BRCA1 or BRCA2 mutation." (PMID 41488281, 2026). "For women at elevated risk for breast cancer due to a BRCA1 or BRCA2 pathogenic variant, RRM can significantly reduce risk while offering a prognosis and life expectancy comparable to that of surveillance, along with reduced fear." (PMID 41438882, 2026). "The highest lifetime risks of developing malignant disease due to inherited BRCA1 and BRCA2 mutations are observed in breast cancer, with rates of 70–80% and 50–60%, respectively." (PMID 40841483, 2026). "Mutations in genes like BRCA2 are well-established in promoting DNA damage and facilitating tumorigenesis in cancers such as breast cancer." (PMID 41139700, 2026). "In one study, 1,583 BRCA1 and 881 BRCA2 mutation carriers with unilateral breast cancer were enrolled in a tamoxifen prevention trial." (PMID 41488281, 2026). "Women with an elevated risk for breast cancer due to a BRCA1 or BRCA2 pathogenic variant can choose for surveillance or risk reducing mastectomy (RRM)." (PMID 41438882, 2026). "Carriers of pathogenic BRCA2 variants have a lifetime risk of developing breast cancer ranging from 38% to 84%, while the risk of developing ovarian cancer ranges from 16.5% to 27.0%." (PMID 41488281, 2026). "Men with a pathogenic BRCA1 variant exhibit a mildly elevated lifetime breast cancer risk of approximately 1%, while those with a pathogenic BRCA2 variant have a lifetime risk of around 8%." (PMID 41528496, 2026). "Women harboring pathogenic variant (PV) in the BRCA1 or BRCA2 genes (= BRCA) have an elevated lifetime risk for breast cancer (BC)." (PMID 42126651, 2026). "PALB2 (partner and localizer of BRCA2) is another crucial gene associated with susceptibility to breast cancer, Fanconi anemia, and other cancers." (PMID 39745016, 2025). "In another study, carriers of impaired BRCA1 genes had a cumulative risk of breast cancer of 72% by the age of 80, and for BRCA2, the corresponding risk was 69%." (PMID 40361383, 2025). "Using this strict approach, we selected two genes associated with a detrimental prognosis: B3GNT7 and CTSV in BRCA2-mut breast cancers, and three with a favorable prognosis: CD6, CXCL9, and CXCL13 in BRCA1-mut ovarian cancers." (PMID 40647506, 2025). "Approximately 20–25% of hereditary breast cancer cases harbor germline mutations in the BRCA1 or BRCA2 genes, which are key breast cancer susceptibility loci." (PMID 41373619, 2025). "In ClinVar, the CFTR gene is related to cystic fibrosis, the BRCA2 gene is associated with breast cancer and breast-ovarian cancer syndrome, and the C3 gene is associated with complement component 3 deficiency." (PMID 39796280, 2025).
breast cancer (continued). "Normal weight (vs. overweight) at menarche and at age 21 were significantly associated with older age of breast cancer onset among women with BRCA1 or BRCA2 mutations." (PMID 40523654, 2025). "When compared to sporadic breast carcinomas and the BRCA2 DNA repair associated (BRCA2) mutant tumors, basal-like breast cancers and tumors arising in carriers of the BRCA1 germ-line mutation exhibit a peculiar pattern of cell cycle protein expression." (PMID 40141415, 2025). "The estimated prevalence of the BRCA1 and BRCA2 pathogenic variant carriers is up to 0.3% in the general population, 3% in women with breast cancer, 6% in women with early onset breast cancer, 10% in women with ovarian cancer, and 20% in high‐risk families." (PMID 39907309, 2025). "Our large-scale retrospective multicenter study found that BCT is comparable with mastectomy in terms of oncologic outcomes for patients with breast cancer who carry BRCA1 or BRCA2 pathogenic variants." (PMID 40366658, 2025). "Our results suggest that BCT can be considered a safe treatment option for patients with breast cancer carrying BRCA1 or BRCA2 pathogenic variants." (PMID 40366658, 2025). "BRCA1 (BRCA1 DNA Repair Associated, also known as Breast Cancer Type 1 Susceptibility Protein) and BRCA2 (BRCA2 DNA Repair Associated, or Breast Cancer Type 2 Susceptibility Protein) encode proteins that function as E3 ubiquitin ligases." (PMID 41008855, 2025). "The presence of BRCA1 and BRCA2 mutations in breast cancer patients has significant implications in treatment decisions, primarily due to the distinct biological characteristics of these tumors and their response to specific therapies." (PMID 41568010, 2025). "Women with germline BRCA1 variants are estimated to have 60%–72% risk of breast cancer to age 70, while those with BRCA2 variants are estimated to have 55%–88% risk." (PMID 39907309, 2025). "Mutations in genes like BRCA1 and BRCA2 are well known for significantly increasing the risk of breast cancer, particularly in hereditary cases." (PMID 40565055, 2025). "This retrospective multicenter cohort study analyzed patients from 13 institutions in South Korea with primary breast cancer with BRCA1 or BRCA2 pathogenic variants who underwent either BCT or mastectomy from January 2008 through December 2015." (PMID 40366658, 2025). "In the recent CARRIERS study, the prevalence of BRCA1 and BRCA2 mutations in women with breast cancer were 2.14% versus 0.35% in non-breast cancer controls." (PMID 39819384, 2025). "Pathogenic variants of BRCA1 and BRCA2 are responsible for approximately 25% of all hereditary breast cancer cases." (PMID 39621070, 2025). "Previous studies showed about 21% of HRD predicted TNBC cases to have pathogenic biallelic loss of BRCA1 or BRCA2 and that approximately 81% of these alterations are germline acquired in the general breast cancer population." (PMID 41327380, 2025). "In a follow-up study within the same population, the BRCA2 Met1915Thr (Thr/Thr) and BRCA2 Met784Val (Met/Met) polymorphisms were reported as potential independent genetic markers for breast cancer susceptibility." (PMID 40843725, 2025). "Germline CNVs overlapping BRCA1 and BRCA2 gene loci associated with the pathogenesis of breast cancer account for less than 5% of known P/LP variants in these genes." (PMID 39858629, 2025). "Among 21 LOF variants related to breast cancer, the allele frequency for one variant (BRCA2:c.9976A > T) was common for breast cancer disease in the gnomAD database." (PMID 41386870, 2025).
breast cancer (continued). "Unlike BRCA1/2 mutation carriers, bilateral breast cancer was not commonly seen in BARD1 mutation carriers, while 29.8% of the BRCA1 and BRCA2 mutation carriers developed bilateral breast cancers (p-value = 0.039)." (PMID 40805222, 2025). "This means that a BRCA1 and BRCA2 mutation determine a particular change in the probability to develop breast cancer." (PMID 40266445, 2025). "More importantly, in two out of four cases with BRCA2 germline mutation, a personal and/or family history of breast cancer was recorded." (PMID 40205657, 2025). "Patients with a BRCA1 or BRCA2 gene mutation are at greater risk of developing breast cancer, often at an early age." (PMID 40142718, 2025). "In contrast, 65% of women carrying a BRCA1 variant and 45% of those with a BRCA2 variant are expected to develop breast cancer later in life." (PMID 40266445, 2025). "Triple negative breast cancer (TNBC) was predominantly observed in BRCA1 mutation carriers, while BRCA2 mutation carriers more commonly presented with the luminal phenotype breast cancer or DCIS." (PMID 41083355, 2025). "Further analyses have investigated potential distinctions between BRCA1- and BRCA2-associated breast cancers." (PMID 41463210, 2025). "Germline mutations in BRCA1 and BRCA2, which account for roughly 15% of hereditary breast cancer cases, compromise DNA repair mechanisms, leading to genomic instability and increased tumorigenesis." (PMID 40243654, 2025). "This study provides important preliminary insights into the potential association between the BRCA2 Met1915Thr polymorphism and breast cancer risk." (PMID 40843725, 2025). "This study aimed to identify the prevalence and mutation spectrum of the BRCA1 and BRCA2 germline mutations among 120 unselected series of Brunei breast cancer patients." (PMID 40531958, 2025). "Pathogenic variants in the BRCA1 and BRCA2 genes are associated with increased risk of developing breast cancer." (PMID 40296163, 2025). "Herein, we present a case of advanced ICC with a breast cancer susceptibility gene-2 (BRCA2) mutation." (PMID 39974545, 2025). "Another study showed an association between a nonsense variant at the carboxyl terminus of BRCA2 (p.Lys3326Ter) with a relative risk of breast cancer of 1.4, substantially lower than the risk conferred by more proximal truncating variants (RR = 11.7)." (PMID 39858629, 2025). "The French Liber Trial compared the efficacy of letrozole compared to a placebo for primary prevention of breast cancer in postmenopausal women carrying BRCA1 or BRCA2 P/LP variants." (PMID 39858629, 2025). "By the age of 70, female carriers of mutations in either Brca1 or Brca2 had a 60–80% likelihood of developing breast cancer." (PMID 40153121, 2025). "BRCA2 mutations are particularly significant, as they confer a lifetime risk of breast cancer of up to 8% in men, which is markedly higher than the general male population risk of 0.1%." (PMID 41502531, 2025). "Approximately 10% of BC cases harbor a germline mutation in the breast cancer genes 1 (BRCA1) or 2 (BRCA2), (gBRCAm), which affects the homologous repair mechanism of DNA double-strand breaks." (PMID 40805203, 2025). "It was shown that three BRCA2 gene variants associated with risk for hereditary breast cancer (rs11571769, rs144848 and rs11571707) had a higher frequency in these individuals compared to African, American, European, and Asian groups." (PMID 40535424, 2025). "Patient #5 had a BRCA2 mutation and had been treated curatively for breast cancer in the affected breast, 2 years before this presentation." (PMID 40464157, 2025). "Worthy of note, a personal or family history of breast cancer was present in three out of five patients with SBAs harboring BRCA2 mutations (including our case)." (PMID 40205657, 2025). "DHC-1, a potent and selective PARP1 inhibitor, selectively inhibited PARP1 activity and showed efficacy in BRCA1-deficient breast cancer and BRCA2-deficient pancreatic cancer cell lines." (PMID 40521389, 2025).